CDK4 (cyclin dependent kinase 4)
Diseases named in the same sentence as CDK4 in open-access papers (continued):
Sharing a sentence is not in itself a finding about the gene and the disease.
melanoma (continued). "The second melanoma predisposition gene described was CDK4, an oncogene that also plays an important role in cell cycle regulation." (PMID 37958811, 2023). "Germline mutations in CDKN2A leading to loss of function and/or CDK4 activating mutations are associated with a 50-fold increased risk of melanoma, according to a study of familial melanoma." (PMID 37081962, 2023). "Another cell-cycle related gene found to be mutated in melanoma-prone families is Cyclin-dependent kinase 4, CDK4." (PMID 36765773, 2023). "P16P2 is a control peptide without the D92A substitution and with an L97R substitution found in a melanoma-susceptible family and reported to impair the binding of p16 to CDK4." (PMID 37522264, 2023). "Hyper-activation of the CDK4/6-Rb-p16INK4A pathway is common and implicated in approximately 90% of melanomas." (PMID 35053435, 2022). "Mutations of the CDKN2A carry a high risk of melanoma, together with CDK4, TERT, and POT1 gene mutations." (PMID 35465855, 2022). "Melanoma is an attractive target for CDK4/6 inhibitors (CDK4/6i) as the p16INK4a/Cyclin D1-CDK4/6/RB pathway is dysregulated in a majority of melanomas, while mutations causing loss or dysfunction of RB itself are uncommon." (PMID 35444175, 2022). "It is therefore likely that in the case of CDK4, the R24C mutation contributes to tumor progression and aggressiveness in melanomas that are initiated by H-ras activation or other changes in gene expression." (PMID 36051751, 2022). "The most important is the suppressor mutation of the CDK4 inhibitor-p17INK6a, which has been analyzed in most melanoma gene lines and primary melanoma samples." (PMID 34422248, 2021). "Germline mutations of CDK4, albeit quite rare, predispose carriers to melanoma development to a similar extent to that observed in individuals harboring CDKN2A mutations." (PMID 34442055, 2021). "CDK4 germline mutations are much less frequent and give rise to a similar clinical phenotype (multiple nevi with melanoma risk)." (PMID 34449585, 2021). "CDKN2A and its binding partner CDK4 were the first melanoma genes to be identified as melanoma-predisposing genes, though mutations in these loci have only been found in 20–45% of familial melanoma cases." (PMID 34356093, 2021). "CDK4 gene amplification has been detected in 50% of glioblastomas (GB) while CDK4 activating point mutation in R24C has been commonly reported in melanoma patients with primary resistance to the INK4 family of CDKIs." (PMID 34445095, 2021). "The CDK4 oncogene is the second identified high-penetrance familial melanoma predisposition gene, playing a pivotal role in the G1/S phase cell cycle checkpoint." (PMID 34123788, 2021). "Recent studies of mucosal melanomas by whole exome sequencing demonstrated that mucosal melanomas have a low mutational burden, with frequent structural variants commonly affecting CDK4, MDM2 and TERT." (PMID 34571863, 2021). "These seminal studies were followed by the first descriptions of mutated peptide neoantigens in melanoma patients within CDK4 and across an aberrantly expressed intron-exon boundary." (PMID 34439399, 2021). "Melanoma show a high frequency of mutations in the CDK4 pathway and CDK4/6 inhibitors have been beneficial in breaking resistance." (PMID 34722291, 2021). "Melanoma cell lines with a Pro81Leu missense mutation in p16INK4a also showed defective binding ability to CDK4, and these cells had more aggressive cell growth compared to the wild-type cells." (PMID 33076392, 2020). "While CDKN2A, BRCA1 protein, and CDK4 genes are known susceptibility genes that are considered to be high risk for melanoma, a well-established clinical utility for testing these gene must first be established." (PMID 33339193, 2020). "Until a few years ago, CDKN2A/ARF (cyclin dependent kinase inhibitor 2A) and its binding partner CDK4 (cyclin dependent kinase 4) were the only known melanoma-predisposition genes tested in clinical practice." (PMID 32325837, 2020).
melanoma (continued). "In a recent report of a multi-gene panel screening of Dutch non-CDKN2A/CDK4 melanoma families, 9 rare pathogenic variants of OCA2 were found." (PMID 32966289, 2020). "About 45% of melanomas have been attributed to germline mutation of predisposition gene CDKN2A, and 2-3% melanomas mutated in gene CDK4 in European and American populations." (PMID 32083130, 2020). "Germline mutations in the gene CDKN2A have been found in about 40% melanoma families and CDK4 alterations in 2-3% families." (PMID 32083130, 2020). "Both, p16Ink4a and p21Cip1 induce senescence by inhibiting CDK4/6, and most genes associated with the resistance of melanoma metastases to ICB were up-stream of CDK4/6." (PMID 32165639, 2020). "These include genes predominantly associated with melanoma (such as CDKN2A and CDK4) but also genes related to multiple solid tumors including melanoma." (PMID 33167923, 2020). "Mutations in CDKN2A are detected in 10–40% of familial melanoma cases, with CDK4 also an established melanoma predisposition gene." (PMID 32987645, 2020). "In particular, mutation occurring in the cyclin-dependent kinase inhibitor 2A (CDKN2A) and cyclin-dependent kinase 4 (CDK4) genes are the most frequent genetic abnormalities associated with melanoma risk." (PMID 32392801, 2020). "Elevated CDK4 activity also occurs in a subset of melanomas, and CDK4 has been implicated in BRAFi resistance." (PMID 32413516, 2020). "CCND1 alone can accelerate the resistance in BRAF-mutant melanoma and is intensified when there is both cyclin D1 overexpression along with a cyclin dependent kinase-4 (CDK4) mutation." (PMID 32092958, 2020). "Both CDKN2A and CDK4 represent high-susceptibility genes for malignant melanoma, i.e., mutation in such genes greatly increases the chance of melanoma development." (PMID 31717496, 2019). "The CDK4 R24C mutation in the BRAFV600E mutant patient 3 was the only additional melanoma-associated mutation predicted to be a driver mutation." (PMID 31795494, 2019). "In patients with advanced melanoma, resistance to PD-1 blockade therapy was reported to be linked to genetic aberrations in the cyclin D–cyclin-dependent kinase 4 (CDK4) pathway." (PMID 31636634, 2019). "In melanoma, activating mutations have so far only been described for CDK4 and are found in melanoma-prone families." (PMID 30858922, 2019). "Most prominent are inhibitory mutations in the CDK4/6-inhibitor p16INK4a, which have been identified in the majority of primary melanoma samples and melanoma cell lines." (PMID 30858922, 2019). "Mutation profiles of the majority of mucosal melanomas suggest potential susceptibility to CDK4/6 and/or MEK inhibitors." (PMID 31320640, 2019). "A CDK4 mutation was later found in two unrelated melanoma families, and the role of CDK4 mutations in melanoma development was confirmed." (PMID 31717496, 2019). "We identify diverse drivers that indicate the majority of mucosal melanomas are potentially susceptible to CDK4/6 and/or MEK inhibitors." (PMID 31320640, 2019). "We propose a restricted panel for BRAF, KRAS/NRAS, KIT, CCDN1, and CDK4 mutations in the routine diagnostic test in order to better classify the SNM subtypes of melanoma." (PMID 31581559, 2019). "The aims of this study were to report the incidence of CDKN2A and CDK4 variants in a series of Greek familial melanoma families and to examine their association with epidemiological and clinical factors, as well as MC1R polymorphisms." (PMID 29774366, 2018). "The CDKN2A gene is frequently mutated or deleted in melanoma tumors, leading to a release in the inhibition of cyclin-dependent kinases CDK4 and CDK6, causing a progression from G1 to S-phase and increased cell cycle activity and proliferation." (PMID 29946532, 2018). "CDKN2A variants were detected in 46.2% of melanoma-prone families, while a CDK4 variant was found in only one family." (PMID 29774366, 2018).
melanoma (continued). "The aims of this study were to evaluate CDKN2A/CDK4 variants in Greek familial melanoma patients and to correlate the mutational status with specific clinico-epidemiological characteristics." (PMID 29774366, 2018). "CDK4/6 inhibition in melanoma cells resulted in apoptosis associated with deregulation of BCL2, BCL2L1, BIRC5 and BIM." (PMID 30349650, 2018). "Two high-penetrance genes, CDKN2A and CDK4, both regulators of the cell cycle, have been first evidenced in around 20% of the families predisposed to melanoma." (PMID 29963229, 2018). "Even though major melanoma predisposing genes such as CDKN2A and CDK4 have been discarded in the MeLiM model, six loci that have been associated with human melanoma show association signals in pigs." (PMID 29963229, 2018). "Having mutations in of CDKN2A and CDK4 is associated with a significant increased risk of malignant melanoma." (PMID 27804060, 2017). "CDKN2A is a tumor suppressor/negative regulator in the CDK4/Rb pathway, and is frequently lost and/or mutated in melanoma, pancreatic cancers, and other tumor types." (PMID 28749946, 2017). "Knockdown of CDK4 in YU2 melanoma cells was associated with reduction in phosphorylated Rb without significantly affecting levels of total Rb or CDK6." (PMID 28915557, 2017). "These are only present in about 2% of a population of melanoma patients, but for melanoma patients with a family history of melanoma 20% to 60% are carriers of mutations in either CDKN2A or CDK4." (PMID 27022491, 2016). "Germline CDKN2A mutations occur in 40 % of 3-or-more case melanoma families while mutations of CDK4, BAP1, and genes involved in telomere function (ACD, TERF2IP,POT1), have also been implicated in melanomagenesis." (PMID 26433962, 2016). "Previous studies have shown that the arginine 24 residue within the CDK4 1-70 amino acid region is essential for CDKN2A-binding, and mutations R24C and R24H of CDK4 were shown to inhibit protein binding with CDKN2A in melanoma." (PMID 27708221, 2016). "Dysregulation of the cyclin D1/CDK4 pathway occurs in a majority of melanomas and increased cyclin D1/CDK4 activity (e.g. loss of p16Ink4A or Fbxo4) cooperates with BrafV600E to drive melanoma." (PMID 27977682, 2016). "Surprisingly, knockin of the CDK4 R24C mutation in mouse models revealed a very low incidence of spontaneous melanomas in CDK4R24C/R24C mice." (PMID 25625291, 2015). "Intact p16INK4a inhibits CDK4 activity and loss of p16, which occurs frequently in melanoma, results in abnormal CDK4 activity." (PMID 26201960, 2015). "Activating mutations, or amplification of CDK4 have been described in both familial and sporadic cases of melanoma." (PMID 26201960, 2015). "In more than 90% of melanoma cases, genomic variations associated with CDK4 pathway activation are present, as determined in human and mouse models of melanoma." (PMID 26252490, 2015). "In fact, the importance of CDK4 protein in human cancers was first highlighted upon identification of a germ line mutation (R24C) that predisposed to melanomas by making it refractory to inhibition by p16INK4a." (PMID 25625291, 2015). "The risk of developing melanomas is also increased by CDK4/cyclin D hyperactivation associated with amplification of cyclin D (18% melanomas) or loss of p16INK4a inhibitor of CDK4/cyclin D (deletion of CDK2NA in 50%–60% metastatic tumours)." (PMID 25625291, 2015). "Germline mutations in high-penetrance melanoma predisposing genes CDKN2A and CDK4 have been found in 20% of familial melanoma cases." (PMID 24982914, 2014). "There are only limited data available on the prevalence of CDKN2A and CDK4 mutations outside the context of familial melanoma." (PMID 25780468, 2014). "Rare alleles of CDKN2A and CDK4 genes have been identified in familial forms of melanoma among patients who have had melanoma." (PMID 24416617, 2013).
melanoma (continued). "Their importance is revealed by the fact that germline and somatic mutations in CDKN2A and CDK4 directly or in their associated signaling pathways are almost invariably found in melanomas." (PMID 24416617, 2013). "Rare deleterious germinal mutations in the cell cycle regulators CDKN2A and cyclin dependent-kinase 4 (CDK4) have been shown to confer a high cutaneous malignant melanoma risk." (PMID 24416617, 2013). "CDK4 is altered in melanoma patients by a miscoding mutation (Arg24Cys) that blocks binding of INK4 inhibitors." (PMID 22932448, 2012). "Melanoma candidate antigens include (A) mutated or aberrantly expressed molecules (e.g. CDK4, MUM-1, beta-catenin) (B) cancer/testis antigens (e.g. MAGE, BAGE and GAGE) and (C) melanoma- associated antigens (MAA)." (PMID 22506061, 2012). "Another melanoma susceptibility gene, CDK4, accounts for only small number of families with germ mutations on chromosome 12q14, encoding a cyclin dependent kinase which normally interacts with p16INK4A." (PMID 22759494, 2012). "Predisposing mutations in CDK4 have been identified in a limited number of melanoma families worldwide." (PMID 22978401, 2012). "Although CDKs are rarely mutated, deregulation of CDK4/6 has been described in various tumors, e.g. in melanoma." (PMID 22443451, 2012). "The second melanoma susceptibility gene is the Cyclin-Dependent Kinase 4, which is located at 12q13.6, and which encodes a protein interacting with the p16CDKN2A gene product." (PMID 19828018, 2009). "This work confirms p16INK4a-driven senescence is intimately linked to CDK4/6-inhibition and cell cycle arrest, and indicates that the melanoma-associated mis-sense p16INK4a mutants are unable to initiate an effective CDK4/6-dependent senescence programme." (PMID 18843795, 2008). "p16INK4a is a highly penetrant melanoma tumour suppressor that regulates cell cycle progression by inhibiting the kinase activities of cyclin D-associated CDK4 and CDK6 (Serrano etal., 1993)." (PMID 18843795, 2008). "Our data provide the first evidence that p16INK4a can initiate a CDK4/6-dependent autonomous senescence programme that is disabled by inherited melanoma-associated mutations." (PMID 18843795, 2008). "CDK2 and p21Cip1 are previously identified MITF target genes in melanoma cells and our data suggest that the melanoma susceptibility gene CDK4 is also an MITF target gene." (PMID 18628967, 2008). "Germline mutations of the CDKN2A gene are found in < 25% of melanoma-prone families and there are only seven families with mutation of the CDK4 gene reported to date." (PMID 18803811, 2008). "The other gene involved in familial predisposition to melanoma, CDK4 is a proto-oncogene that promotes cell cycle progression by phosphorylating the Rb protein." (PMID 15928671, 2005). "Germline anomalies of the INK4a-ARF and Cdk4 genes were sought in a series of 89 patients suspected of having a genetic predisposition to melanoma." (PMID 14735200, 2004). "This confirms previous studies performed in melanoma families, and further shows that the Cdk4 gene is very rarely involved in genetic predisposition to melanoma." (PMID 14735200, 2004). "The germline CDK4 R24C mutation is also found in melanoma-prone families, albeit rarely." (PMID 40282469, 2025). "Similarly, the point mutation CDK4R24C in hereditary melanoma patients abolishes the interaction with p16INK4a leading to elevated CDK4 kinase activity." (PMID 39898030, 2025). "Thus, due to their low frequency, CDK4 mutations’ contribution to familial melanoma risk still remain difficult to be accurately assessed." (PMID 40869905, 2025).
melanoma (continued). "This cross-signaling mechanism explains the selection of oncogenic Gnaq/11 in primary Hgf-Cdk4 melanomas and provides an example of how oncogenic driver mutations, intracellular signaling cascades, and microenvironmental cues cooperate to drive cancer development in a tissue-specific fashion." (PMID 38360887, 2024). "Besides CDKN2A, other genes potentially associated with familial melanoma have also been investigated in Brazilian melanoma-prone families, such as CDK4, MITF, and TERT promoter variants." (PMID 37958811, 2023). "CDK4, for example, has been well documented that is closely associated with melanoma." (PMID 37081962, 2023). "Moreover, WES data on the biopsies from a melanoma patient showed that the oncogenic mutation PI3KCAE545K pre-existed in a rare tumor cell subpopulation prior to combination therapy of the CDK4/6 inhibitor ribociclib and the MEK inhibitor MEK162." (PMID 35892870, 2022). "The CDK4-Arg24Cys (R24C) mutation was also detected in sporadic melanomas, suggesting that a CDK4 gene containing this mutation could act as a dominant oncogene that is resistant to normal physiological inhibition by p16INK4A." (PMID 36051751, 2022). "A previous study in melanoma found that S6K1 inhibition can revert PIK3CA mutation-induced resistance to CDK4/6 inhibitor, while the specific molecular mechanism remained unknown." (PMID 36042494, 2022). "Therefore, CDK4 copy-number gain would be associated with resistance to anti-PD-1 therapy in melanoma." (PMID 35013211, 2022). "Notably, palbociclib has been approved to treat estrogen-positive breast cancer with a high proliferation index (measured by Ki-67), and clinical trials investigating its effectiveness in CDK4 mutated melanomas are underway." (PMID 35465855, 2022). "However, germline mutations in the CDK4 are quite rare, having recently been discovered in families of hereditary malignant melanoma." (PMID 34735543, 2021). "The germline mutation in CDK4 has been analyzed in hereditary melanoma families." (PMID 34422248, 2021). "For the let-7a family members, under-expressed in both L-Tyr and 5-Brd-2′-dU or let-7b overexpressed in 5-Brd-2′-dU and reported as a cell cycle regulator in melanoma, possibly through cyclins D1 and D3 and Cdk4 and associated with interference with anchorage-independent growth." (PMID 33562431, 2021). "The first group is represented by intrinsic or constitutional factors: familiar and genetic factors (familiarity for melanoma cases, mutations of susceptibility genes, such as Cyclin-dependent kinase 4 (CDK4)) and skin features (number of nevi, presence of atypical nevi, and phenotype/phototype)." (PMID 34836273, 2021). "In addition, fibroblast infiltration associated with CDK4 cancer was observed in head and neck, sarcoma, and melanoma skin." (PMID 34422248, 2021).